CCR8 (C-C motif chemokine receptor 8)
Diseases named in the same sentence as CCR8 in open-access papers (continued):
Sharing a sentence is not in itself a finding about the gene and the disease.
tumor (continued). "In circulating CD8+ T cells from patients whose tumor achieved pCR, there was higher expression of cell adhesion molecules (CD62L, CCR8, CD49d, CD18), as well as TIGIT (which was also increased in intratumoral CD8+ T cells in pCR versus non-pCR pre-sotigalimab)." (PMID 38181044, 2024). "The anti-CCR8 antibody of rat IgG2b isotype was injected intravenously into EMT6 BC cell-treated mice and was found to highly inhibit tumor growth with greater than 50% tumor clearance." (PMID 39329710, 2024). "Furthermore, in both anti-programmed cell death protein 1 (anti-PD1)-responsive and anti-PD1-unresponsive tumour models, PD1 blockade induced CCR8+ Treg infiltration." (PMID 37935468, 2024). "Studies utilizing CCR8 knockout mice revealed no alteration in the recruitment, activation, and immunosuppressive capacity of TITRs, and no impact on tumor growth." (PMID 38231448, 2024). "Moreover, the depletion of Tnfr2 or blockade of TNFR2 inhibited tumour growth and enhanced the therapeutic efficacy of the anti-PD1 mAb by reducing CCR8+ Treg invasion." (PMID 37935468, 2024). "Studies have shown that CCR8-DNR-CAR-T cells are recruited in large quantities to tumor sites, but not to other normal organ tissues." (PMID 39136031, 2024). "Our study revealed the relationship between two markers (TNFR2 and CCR8) of tumour-infiltrating Tregs and suggested TNFR2+CCR8+ Tregs as a potential immunotherapeutic target to enhance antitumour immunity and strengthen anti-PD1 treatment efficacy in CRC patients." (PMID 37935468, 2024). "We observed that CCL18 was highly expressed in tumour-infiltrating CD68+ macrophages, which attracted Tregs via the CCL18/CCR8 interaction, so we speculated that CCL18+ macrophages could lead to the accumulation of CCR8+ Tregs in the TME." (PMID 37935468, 2024). "CCR8-/- mice did not have altered numbers and proportions of Tregs in the tumor and spleen, nor did CCR8 deletion affect the growth of MC38-transplanted tumors." (PMID 37182149, 2023). "In this study, we compared differences in gene expression profiles between peripheral circulation and tumor tissue infiltrated CD4+ T cells, and analyzed the correlation between the level of CCR8 expression on CD4+ T cells from different sample sources and clinical characteristics." (PMID 37950246, 2023). "We found that NUP107 was positively correlated with chemokines such as CCL28 and CXCL8 (r = 0.310, p < 0.001), and the chemokine receptors CCR8 and CXCR4 suggesting that NUP107 overexpression may recruit immune cells to the tumor tissues." (PMID 36952458, 2023). "We found that the frequency of CCR8+ CD25+ FOXP3− Tconv cells inversely correlates with the frequency of tumor-infiltrating CD8+ T cells, suggesting that they play an inhibitory role in human tumor immunity." (PMID 38100544, 2023). "Unlike CCR4, the target of mogamulizumab, CCR8 was selectively expressed on tumor Tregs and minimally expressed on effector T cells." (PMID 36765704, 2023). "Chemokines secreted by TAMs, including CCL3, CCL5, CCL15, CCL18, CXCL8 and CXCL12, promote tumor metastasis, angiogenesis, cancer cell survival, immunosuppression and resistance of cancer cells after chemotherapy via CCR1/5, CCR5, CCR1, CCR8, CXCR1/CXCR2, CXCR4, respectively." (PMID 36173487, 2023). "The C-C motif chemokine receptor 8 (CCR8) is a class A G protein-coupled receptor (GPCR) that is highly enriched and selectively expressed on intratumoral regulatory T (Treg) cells, which act as suppressors of anti-tumor effector T cell responses." (PMID 38040762, 2023). "In addition, anti-CCR8 CAR T cells exhibited antitumor activity against ATLL cells and CCR8-expressing T-ALL cells, and prolonged the survival of ATLL and Jurkat tumor-bearing mouse models." (PMID 35693763, 2022). "Approximately 40% of the expanded Tregs expressed CCR8 (data not shown) and Treg-related molecules were expressed at higher levels in the CCR8+ fraction than the CCR8− fraction (n = 8) as with tumor-infiltrating Tregs." (PMID 35354899, 2022).
tumor (continued). "Interestingly, the close association of the DTL gene and markers of Treg cells and T cell exhaustion, such as FOXP3, CCR8, STAT5B, PD-1, CTLA4, and LAG3, was found after adjusting the correlation values for tumor purity." (PMID 35392073, 2022). "Therefore, these collective results suggest that C1928z T cells and C1028z T cells can suppress the growth of CCR8-expressing T-ALL tumors and improve the overall survival of tumor-bearing mice." (PMID 35693763, 2022). "Notably, anti-CCR8 CAR T cells reduced Jurkat tumorigenesis and prolonged survival of Jurkat tumor-bearing mice." (PMID 35693763, 2022). "Importantly, anti-CCR8 CAR T cells exhibited antitumor effects on ATLL- and other CCR8-expressing T-ALL cells in vitro and in vivo, and prolonged the survival of ATLL and Jurkat tumor-bearing mouse models." (PMID 35693763, 2022). "Moreover, both the CF1 and total TI Treg signatures had superior discrimination ability when compared to previously reported tumor Treg markers, such as FOXP3 and ratio-based signatures CCR8:FOXP3 or CCR8:CD3G 12,13." (PMID 34599187, 2021). "Indeed, gene set enrichment and leading-edge analyses of activated, (shared) tissue, inflammatory and tumor-infiltrating Treg cell gene sets amongst others revealed sharing of the core eTreg cell genes, including BATF, CCND2, CCR8, TNFRSF18, and VDR." (PMID 33976194, 2021). "We then analyzed whether the OSCC tumor secreted-factors defined as secretome, were promoting these phenotypes and we observed that the OSCC secretome induced CCR8 expression and reduced cytokine production on both subsets." (PMID 34025655, 2021). "Tumor-infiltrating Tregs have been shown to exhibit a distinct signature comprising the co-stimulatory molecules (OX40, 4-1BB), cytokine receptors (IL1R2, IL21R, CCR8, CD30), and co-inhibitory molecules (PD-L1, TIGIT)." (PMID 33527196, 2021). "Overall, and in accordance with the observations in CCR8-KO mice, CCR8 blockade by itself appears not to be sufficient to affect tumor growth." (PMID 33589525, 2021). "Notably, CRC tumor-infiltrating Tregs can be distinguished by the increased expression of a panel of signature markers, including CD30, IL1R2, IL21R, OX40, CCR8, PD-L1, TIGIT, and 4-1BB." (PMID 33527196, 2021). "All these results demonstrate that different chemokine receptor/ligand pairs contribute to Treg recruitment at the tumor site, according to specific contexts; however, CCR4 and CCR8 appear as the most selectively expressed on TA-Tregs compared to Tregs from the periphery or the healthy tissues." (PMID 33924428, 2021). "Interestingly, the expression levels of CCR8 and P2RY14 in tumor tissues were significantly correlated with gender, with women showing significantly higher levels of gene expression than men." (PMID 33692955, 2021). "Interestingly, also the density of CCR8 surface expression (as measured by MFI) on CCR8+ Tregs gradually increased from thymus, to spleen and further to tumor-draining lymph node and TME." (PMID 33589525, 2021). "Our phenotypic data revealed a higher distribution of tumour-infiltrating CCR8+ and Th2-like Treg in OSCC compared with non-malignant samples, whereas the percentages of Th1 cells were reduced in cancer." (PMID 34025655, 2021). "These CCR8+ TAM that display activated STAT3 are capable to increase the FOXP3 expression in infiltrating CD4+ T cells, suggesting the generation of iTregs that will favor tumor progression." (PMID 33924428, 2021). "Expression of CCR8 is noted in several types of immune cells including T regs, monocytes, peritoneal macrophages, Langerhans cells and NK cells, but not in tumor cells." (PMID 31811337, 2020). "In whole-tumor samples, overexpression of LAYN, MAGEH1, and CCR8, three of the most enriched genes in tumor-infiltrating Treg signature genes, was associated with a worse 5-year survival of CRC and NSCLC patients, pinpointing these genes as potential therapeutic targets." (PMID 29879107, 2018).
tumor (continued). "The expression of CCR8 on MF or SS tumor cells has not been reported, although the mRNA expression of CCR8 is known to be upregulated in patients with SS." (PMID 29915722, 2018). "Several chemokine-chemokine receptor pairs have been proposed to be responsible for recruiting Tregs to tumors including chemokine receptors CCR4, CCR10, CCR8 or CXCR3 expressed on infiltrating Tregs, responding to CCL22, CCL28, CCL1 or CXCL9-11 in the tumor microenvironment, respectively." (PMID 28290464, 2017). "Positive CCR8 staining tumor cell occurred in 26.1% (123 of 472) non-metastatic ccRCC cases, and the positive expression was associated with increased risks of recurrence (Log-Rank P < 0.001)." (PMID 26716905, 2016). "Our data indicate that CCR8 and CXCR4 are up-regulated on tumor-infiltrating FoxP3+ T cells." (PMID 22292042, 2012). "Moreover, antibodies targeting CCR8 such as GS-1811, S-531011, and 2MW4691 allow for highly specific depletion of tumor-resident Tregs via antibody-dependent cellular cytotoxicity (ADCC), promoting the expansion of CD8+ T cells and improving tumor control." (PMID 41394821, 2025). "IL-4 and IL-13, cytokines abundantly produced in later stages of MF and in SS, can enhance CCR8 expression on malignant T cells and may stimulate keratinocytes and myeloid cells to secrete CCL1, thereby creating a positive feedback loop for tumor cell recruitment and survival in the skin." (PMID 40861461, 2025). "Given that intratumoral Tregs have been shown to express CCR8133, another approach is to consider the Fc-optimized anti-CCR8 antibody, which was shown in murine models to selectively deplete intratumoral Tregs and not peripheral Tregs, resulting in impaired tumor growth." (PMID 39803458, 2025). "Additionally, anti-CCR8 treatment induces persistent anti-tumor responses without triggering harmful autoimmune effects." (PMID 40607438, 2025). "In CRC patients, high levels of tumour-infiltrating TNFR2+CCR8+ Tregs, but not total Tregs, were associated with an adverse prognosis, indicating that TNFR2+CCR8+ Tregs might play important roles in the progression of CRC." (PMID 37935468, 2024). "Likewise, CCR8-blocking antibodies lacking ADCC effect showed no efficacy in suppressing tumor growth." (PMID 38231448, 2024). "Notably, chemokine receptors, including C-C chemokine receptor type 2, 4, 5, 6, 8, 10 (CCR2, CCR4, CCR5, CCR6, CCR8, CCR10), and C-X-C chemokine receptor type 3, 4 (CXCR3, CXCR4) have been identified as significant factors in the recruitment of Treg cells to the tumor site." (PMID 39000453, 2024). "Lactate accumulation upregulated CD39, CD73, and CCR8 expression through histone H3K18 lactylation, suggesting that targeting lactate metabolism could reprogram glucose metabolism and alleviate immunosuppression in the tumor microenvironment." (PMID 39766353, 2024). "Particularly, CCR8 antibodies capable of inducing antibody-dependent cellular cytotoxicity (ADCC) have demonstrated their ability to selectively eliminate TITRs within tumor sites, resulting in reduced tumor growth without causing side effects." (PMID 38231448, 2024). "We speculated that patients with a high infiltration of CCR8+ Tregs in tumors may not form an immunological memory and are thus more liable to show tumor metastasis and a shorter DFS." (PMID 35354899, 2022). "Results from this study suggested that patients with CRC may harbor tumor-infiltrating Tregs with a specific protein signature, including the co-stimulatory molecules (OX40, 4-1BB), cytokine receptors (IL1R2, IL21R, CCR8, CD30), and co-inhibitory molecules (PD-L1, TIGIT)." (PMID 33527196, 2021). "In addition, the contribution of CCR8 to the function of NK cells and monocytes within tumours was not resolved." (PMID 33838058, 2021).
tumor (continued). "We observed no changes in the frequency of total CD4+ Tconv cells in the spleens or tumours of Ccr8−/− mice compared to Ccr8+/+ animals but did not in this study examine whether there were differences in the composition of the CD4+ Tconv compartment." (PMID 33838058, 2021). "Thus, while we observed no overall difference in Treg cell infiltration and tumour immunity in the absence of CCR8, it will be important to examine its functions in greater cellular and molecular resolution in future studies." (PMID 33838058, 2021). "Hence, while treatment with a combination of anti-PD-1 and anti-CCR8 (Nb-Fc1B) significantly affects tumor growth, it does not induce gut inflammation." (PMID 33589525, 2021). "We would like to emphasise that our observations are not inconsistent with the recently reported ability of anti‐CCR8 antibodies to reduce tumour growth in syngeneic tumour models in mice, but suggest a re‐interpretation of the mechanism underlying these observations." (PMID 33838058, 2021). "In this study, we detected the expression in tumor cells from a segment of non-metastatic ccRCC cases detected and confirmed the intratumoral CCR8 expression in 26% (123 of 472) ccRCC tissue samples, comparative with that of 16% reported by 2013 TCGA cohort data." (PMID 26716905, 2016). "However, subsequent single-cell RNA sequencing of the LLC-OVA tumor-infiltrating TCRβ+ cell compartment revealed that Ccr8 expression was not restricted to ti-Tregs, but could also be found in populations of dysfunctional CD4+ and CD8+ T cells." (PMID 33589525, 2021). "Interestingly, in tumor-bearing mice, upregulation of CCR8 expression on Tregs could already be detected in the tumor-draining lymph node and spleen, but not in any other tissue except the thymus." (PMID 33589525, 2021). "Therefore, the mechanism for activation of CTLs specific for tumor cells might not be the same in the case of an anti-CCR8 antibody for depletion of local Tregs and the case of a DHP column for depletion of blood LAP+ T cells, for example priming of CTLs in the secondary lymphoid organs." (PMID 40053558, 2025). "As expected, the injection of CD8+ T cells significantly suppressed tumour growth, whereas the injection of CD8+ T cells plus TNFR2+CCR8+ Tregs had no inhibitory effect on tumour growth progression." (PMID 37935468, 2024). "Next, we isolated tumour-infiltrating TNFR2+CCR8+ Tregs and TNFR2−CCR8− Tregs from tumour tissues and found that TNFR2+CCR8+ Tregs, rather than TNFR2−CCR8− Tregs, strongly suppressed the proliferation of CD8+ T cells." (PMID 37935468, 2024). "CCR8 is highly expressed in the tumor microenvironment, especially in Tregs, whereas NK cells, CD8 + T cells, myeloid cells, and most CD4 + T cells do not express CCR8." (PMID 38915099, 2024). "We found that besides TNFRSF4, Treg functional signature genes such as FoxP3, CTLA4, TIGIT, TNFRSF18 (GIRT), CCR8, LAYN, and MAGEH1 were also overexpressed in C11-Tregs-FoxP3 of treatment-naive and non-MPR tumor lesions, but not for MPR tumor lesions." (PMID 35831283, 2022). "CCR8 and P2RY14 were significantly differentially expressed in tumor tissues compared with normal tissues, while CCR4 was not significantly different." (PMID 33692955, 2021). "Furthermore, monoclonal antibody (mAb) therapy against CCR8 significantly reduced de novo induction and suppressive function of Tregs without affecting CD8+ T cells, delayed tumor growth, and improved long-term survival in CRC mouse models." (PMID 33419310, 2020). "We further deepened the concept and found that CCR8+ Treg cells, unlike tradition FOXP3+ Treg cells, displayed high expression of exhaustion and cytokine receptors and strongly correlated with inflammatory response, suggesting its highly activated and tumor-reactive phenotypes." (PMID 38897205, 2024).
tumor (continued). "Similarly, increased levels of adhesion molecules in circulating CD4+ T cells (CCR8, CD18) and monocytes (CD18, CCR8, Cd49f, CD54, LFA-3, P-selectin, CD29) were observed in baseline samples from patients whose tumor had pCR compared with those that did not have pCR." (PMID 38181044, 2024).
cancer (60 papers, 2016 to 2025). A tumor composed of atypical neoplastic, often pleomorphic cells that invade other tissues. "Specifically, the increase of intratumoral CCR8+ Tregs has been associated with a poor prognosis in various cancers including CRC." (PMID 40305493, 2025). "The analysis shows that CCR8 expression is correlated with TMB and MSI in several cancers, suggesting that higher CCR8 levels may be associated with increased genomic instability and mutation rates in tumors." (PMID 39273290, 2024). "Based on these considerations, it is unlikely that CCR8-specific antibodies will cause irAEs exceeding those observed in patients treated with mogamulizumab (see review article by O. Yoshie in this Special Issue in Cancers)." (PMID 35158783, 2022). "A dramatic expansion of CD4+CD8+ double positive (DP) T lymphocytes was observed on Day 3 post administration of 225Ac-anti-CCR8 in both cancer models (CT26: p=0.0234, MC38: p<0.0001)." (PMID 41035646, 2025). "Further investigation of anti-CCR8 RIT as a potential cancer-agnostic agent and its combinations with other immunotherapy agents such as anti-PD-1, LAG3 or TIGIT is warranted." (PMID 41035646, 2025). "This study highlights the potential of CCR8 as a biomarker and therapeutic target, contributing to the development of targeted cancer treatment strategies." (PMID 39273290, 2024). "Collectively, these findings suggest that CCR8 targeting represents a promising strategy for Treg depletion in cancer therapies." (PMID 38856863, 2024). "Many CCR8 monoclonal antibodies have been produced by hybridomas to explore their biological function and cancer immunotherapy." (PMID 38721308, 2024). "It has been shown that CCR8 activation can rescue cancer cells from dexamethasone-induced apoptosis or potentiate the survival of Tregs in the presence of dendritic cells." (PMID 38231448, 2024). "The findings emphasize the significance of the CCR8 as potential therapeutic targets and prognostic markers for enhancing cancer immunotherapy." (PMID 39273290, 2024). "The C-C motif chemokine receptor 8 (CCR8) is a class A G-protein coupled receptor that has emerged as a promising therapeutic target in cancer." (PMID 38040762, 2023). "Depleting CCR8+ Tregs showed a strong antitumor effect on its own or in combination with a PD-1 inhibitor in mouse models of cancer." (PMID 36765704, 2023). "While C-C chemokine receptor 8 (CCR8) has been investigated as a candidate anti-cancer target, comprehensive multi-omics analyzes across various indications are limited." (PMID 38001911, 2023). "Data on targeting CCR8 in cancer thus far, however, has been conflicting, but some preclinical models have shown promise." (PMID 38283365, 2023). "This research advances our understanding of CCR8 as a potential target for anti-cancer drug development, bridging the gap between molecular insights and creating opportunities for personalized treatment of solid tumors." (PMID 38001911, 2023). "KC;iASPPΔ8/Δ8 pancreas-infiltrating γδ T cells expressed higher amounts of CCR8 (p = 2.1 × 10–3), whose expression strongly correlates with worse cancer prognosis, and 41% of KC;iASPPΔ8/Δ8 pancreas-infiltrating γδ T cells expressed PD-1H." (PMID 36746936, 2023). "In this study, we conducted an extensive bioinformatics analysis integrating genomics, proteomics, and transcriptomics data to establish CCR8 as a promising anti-cancer drug target." (PMID 38001911, 2023). "CCR8’s more recent identification as a chemokine receptor specifically upregulated in cancer Tregs and it’s correlation with poor outcomes in patients has garnered significant interest." (PMID 38283365, 2023). "Chemokines, such as CCL28, CXCL8, and CXCL16, and chemokine receptors, including CCR1, CCR8, and CXCR2, were positively linked to DLAT expression in various cancers." (PMID 37199628, 2023).